IL9 (interleukin 9)
Diseases named in the same sentence as IL9 in open-access papers (continued):
Sharing a sentence is not in itself a finding about the gene and the disease.
airway allergy (4 papers, 2017 to 2021). "The rationale of this strategy stems from the notion that JAK is a tyrosine kinase involved in the signaling of T cell receptor and of several cytokines that play a pivotal role in allergic respiratory disease, such as IL-2, IL-4 and IL-9." (PMID 34680614, 2021). "The rationale of this strategy derives from the data that JAK is a tyrosine kinase involved in the signaling of T cell receptor and of several cytokines that play a role in allergic respiratory disease, such as IL-2, IL-4 and IL-9." (PMID 34680614, 2021). "Moreover, the transcription factor FOXO1, which was recently described to be essential for Th9 cell differentiation and IL-9 production, was clearly reduced upon Tgfbr2 ablation, correlating with reduced airway allergy." (PMID 35069535, 2021). "Thus IFN-γ/IRF1 signalling restricts Th9-mediated airway allergy in an IL-9-dependent manner while enhancing IFN-γ production in Th9 cells, indicating that IRF1 constrains allergic airway disease by skewing Th9 cells towards a ‘low-allergic' IFN/Th9 phenotype." (PMID 28497800, 2017).
anaplastic large cell lymphoma (4 papers, 2014 to 2024). Anaplastic large cell lymphoma (ALCL) is a rare and aggressive peripheral T-cell non-Hodgkin lymphoma, belonging to the group of CD30-positive lymphoproliferative disorders, which affects lymph nodes and extranodal sites. "Experimental analysis of tissue sections also demonstrated a unique association between IL-9 expression and the development of HD and anaplastic large cell lymphoma (ALCL)." (PMID 27364124, 2016). "The dysregulation of IL-9 and IL-9R could be detected in the biopsy specimens and serum of patients with HL, anaplastic large cell lymphoma (ALCL), and nasal NK/T cell lymphoma." (PMID 35211408, 2022).
appendicitis (4 papers, 2019 to 2024). Acute inflammation of the vermiform appendix. "This cohort study aimed to evaluate the association of serum concentrations of IgE, IL-4, IL-9, and IL-13 in children with the risk of complicated appendicitis." (PMID 35586830, 2022). "The aim of the present study was to evaluate whether concentrations of IgE and the Th2-associated cytokines interleukin (IL)-4, IL-9 and IL-13 in serum are associated with the risk of complicated appendicitis in children." (PMID 35586830, 2022). "Children with complicated appendicitis had significantly higher concentrations of IL-9 and IL-13 compared to children with uncomplicated appendicitis." (PMID 35586830, 2022). "Here, we propose the concept of appendicular lavage and use it to study the levels of the Th2 cytokines IL-4, IL-5, and IL-9 in patients with a clinical diagnosis of acute appendicitis." (PMID 31772507, 2019). "Serum concentrations of IL-4 and IL-9 did not affect the risk of complicated appendicitis, but at the same time high levels of IL-13 were associated with an increased risk of complicated appendicitis." (PMID 38673802, 2024). "Serum concentrations of IgE, IL-4, and IL-9 did not significantly affect the risk of complicated appendicitis." (PMID 35586830, 2022). "High concentrations of serum IL-13 seem to be associated with an increased risk of complicated appendicitis in children, while serum total IgE, IL-4 and IL-9 do not seem to be associated with the risk of complicated appendicitis." (PMID 35586830, 2022). "When comparing phlegmonous appendicitis values with those of NPA, the difference was significant (p = 0.01): IL-4 (48.3 vs. 21.3 pg/mL), IL-5 (29.2 vs. 8.0 pg/mL), and IL-9 (34.1 vs. 16.6 pg/mL)." (PMID 36499410, 2022). "IgE, IL-4, and IL-9 concentrations did not affect the risk of complicated appendicitis in the crude or the adjusted analysis: IgE aOR 0.53 (95% CI 0.329–1.181, p = 0.12), IL-4 aOR 1.08 (95% CI 0.59–1.99, p = 0.81), and IL-9 aOR 1.05 (95% CI 0.93–1.19, p = 0.46)." (PMID 35586830, 2022). "Differences in IL-4, IL-5, and IL-9 in AL fluid were found between the 3 study groups and especially significant between phlegmonous and negative appendicitis." (PMID 31772507, 2019). "The difference was more pronounced when comparing phlegmonous appendicitis with nonpathological appendicitis (p = 0.01) for IL-4 (48.3 vs. 21.3 pg/mL), IL-5 (29.2 vs. 8.0 pg/mL), and IL-9 (34.1 vs. 16.6 pg/mL)." (PMID 31772507, 2019).
candidiasis (4 papers, 2018 to 2025). Infection with the organism Candida. "It is tempting to speculate that IL-9 SNPs might not only influence the risk of Aspergillus allergy, especially in females, but could also impact the risk of Candida infection." (PMID 30515173, 2018). "However, in other settings, such as candidiasis, IL-9 has been shown to play a proinflammatory role by promoting NLRP3 inflammasome activity in the early stages of infection and, in the late stages, a tolerogenic role by promoting IL-1Rα production." (PMID 40962954, 2025). "Accordingly, the IL-9 neutralization early in infection ameliorates inflammation and restores epithelial homeostasis suggesting a potential therapeutic use of IL-9 neutralizing antibody in the treatment of Candida infection." (PMID 30515173, 2018). "Confirming our initial day 3 PI, intracellular flow, Nos3-/- mice showed significantly higher Th9 subset (CD4+IL-9+) and Th2 subset (CD4+IL-4+) induction due to dissemination candidiasis at days 2–6 PI." (PMID 31671151, 2019).
dengue (4 papers, 2012 to 2025). "In the literature, IL-1β elevations in dengue patients align with inflammasome activation during infection, and meta-analyses/studies show significant IL-4 and IL-9 increases in acute dengue, consistent with our Th2-associated signals." (PMID 41346606, 2025). "High levels of VEGF have been reported in KU812 and HMC-1 supernatant when infected with DENV-2 in the presence of human dengue-immune serum, and it was even higher in the presence of IL-9." (PMID 36297236, 2022). "The levels of IL-9 and IL-17 in Dengue patients on day 0, and those in blood samples collected from febrile illness and healthy subjects were measured by ELISA." (PMID 22363824, 2012). "As IL-9 has been reported as a T cell-derived mast cell growth factor and more recently, is implicated as a Th17-derived cytokine that can contribute to inflammatory diseases, we investigated the involvement of IL-9 and IL-17 in Dengue virus infection." (PMID 22363824, 2012). "We found comparable levels of IL-4 between Dengue patients and control groups, suggesting the involvement of IL-9 and -17 in Dengue virus infection." (PMID 22363824, 2012). "This study demonstrated that the Th2-biased cytokine storm pattern observed in hTim4 mice with DENV-2 infection, characterized by elevated levels of Il6 (**P = 0.0082), Il9 (P = 0.3965), Il10 (*P = 0.0168), was highly consistent with the serum profiles of clinical dengue fever patients." (PMID 40623122, 2025). "To evaluate the contribution of IL-9 and IL-17 to Dengue virus infection, we measured the plasma levels of these two cytokines in Dengue patients and found that both IL-9 and IL-17 were significantly increased in DHF and DSS compared with DF, febrile illness and healthy subjects." (PMID 22363824, 2012). "In conclusion, we found that mast cells and mast cell-derived mediators, namely VEGF, and the mast cell-specific proteases tryptase and chymase participate in the development of severe forms of Dengue virus infection, which is accompanied by elevated circulating levels of IL-9 and -17." (PMID 22363824, 2012). "Although these results suggested that IL-9 and IL-17 participate in Dengue virus infection, IL-9 may act additively or synergistically with other factors, such as other Th2 cytokines, to induce optimal mast cell responses." (PMID 22363824, 2012). "As IL-9 enhances the survival of mast cells and induces their production of proinflammatory cytokines, including Th1 and Th2 cytokines, it is possible that IL-9 primes HMC-1 and KU812 cells in vitro to respond to Dengue virus infection by promoting VEGF production." (PMID 22363824, 2012). "However, as the level of IL-4 was not increased in the plasma of Dengue patients, our findings suggest the independent involvement of IL-9 secreted by Th2 cells in Dengue virus infection." (PMID 22363824, 2012).
diabetic kidney disease (4 papers, 2022 to 2025). Progressive kidney disorder caused by vascular damage to the glomerular capillaries, in patients with diabetes mellitus. "IL-9 was also strongly correlated with VEGF, TNFα and IL-6 all of which have all been previously implicated in diabetic nephropathy." (PMID 35445345, 2022). "IL-9 has gained particular attention for its potential role in diabetic nephropathy (DN)." (PMID 40804870, 2025). "Bermejo's study mentions that tumor necrosis factor-alpha (TNF-alpha) and interleukin-9 (IL-9) levels in the urine were higher in this group when compared to other kidney pathologies that were biopsied, such as acute tubular necrosis, diabetic nephropathy, or glomerulopathies." (PMID 38516472, 2024). "They did find that IL-9 levels increased in participants with diabetic kidney disease." (PMID 35445345, 2022). "In an exploratory analysis, we also studied interactions between IL-9, the albumin/creatinine ratio (ACR) and urinary cytokines linked to the progression of diabetic nephropathy: vascular endothelial growth factor (VEGF), interleukin-6 (IL-6) and tumor necrosis factor alpha (TNFα)." (PMID 35445345, 2022). "Interleukin-9 (IL-9) attenuates podocyte injury in experimental kidney disease, but its role in diabetic nephropathy is unknown." (PMID 35445345, 2022). "Although IL-9 may limit podocyte injury in early diabetic kidney disease, its role in advanced disease is less clear." (PMID 35445345, 2022).
endometriosis (4 papers, 2018 to 2024). The growth of functional endometrial tissue in anatomic sites outside the uterine body. "Elevated levels of IL-9 were also causally associated with endometriosis, while a potential positive association was detected for IL-2 with endometriosis, albeit using less reliable measures." (PMID 39766252, 2024). "We also found that circulating IL-9 was positively causally associated with endometriosis in IVW analysis." (PMID 39766252, 2024). "In our primary IVW analyses, IL-9 was positively causally associated with endometriosis, with an odds ratio of 1.15." (PMID 39766252, 2024). "In Bonferroni-corrected leave-one-out analyses, omitting single SNPs did not achieve statistical significance for exposures associated with PCOS (MCP-1/CCL2: p > 3.85 × 10−3, 0.05/13) or endometriosis (IL-2: p > 0.01, 0.05/5; IL-9: p > 8.33 × 10−3, 0.05/6)." (PMID 39766252, 2024). "Since IL-8 contributes to the adhesion, invasion, and proliferation of endometriotic lesions, it was posited that IL-9 indirectly contributes to the development or progression of endometriosis by inducing IL-8 expression." (PMID 39766252, 2024). "The exact mechanisms by which IL-9 contributes to the pathophysiology of endometriosis, whether directly or via stimulating other pro-inflammatory mediators, remain poorly understood." (PMID 39766252, 2024). "Replication of our findings and additional mechanistic investigations are encouraged to determine whether modulating circulating IL-9 levels may offer tangible benefits for the treatment and management of endometriosis." (PMID 39766252, 2024). "However, one SNP was individually associated with endometriosis in the IL-2 (rs4634519, p = 0.0082; p < 0.01, 0.05/5), but not IL-9 analysis (p > 8.33 × 10−3, 0.05/6)." (PMID 39766252, 2024). "Lastly, while MCP-1/CCL2 and IL-9 are proposed as potential biomarkers for PCOS and endometriosis, respectively, supported by pre-clinical and observational data, their specificity in real-world clinical applications remains uncertain." (PMID 39766252, 2024). "However, PBS-Treated Mice also showed decreased plasma levels of Eotaxin, IL-9, IL-13, and MIP-1α, suggesting that the difference may stem from the induction endometriosis, and not from the IL-17A injection." (PMID 32117261, 2020).
fungal infection (4 papers, 2015 to 2024). "Anti-inflammatory cytokines such as IL-3, IL-4, IL-5, IL-9, IL-10, and IL-13 were also induced within 3 h of fungal infection in all three groups of mice and remained high up to the 7th day period." (PMID 38783167, 2024). "IL-17A mediates host resistance to extracellular bacterial and fungal infections by acting as a powerful inducer of neutrophil growth factors, such as granulocyte colony stimulating factor (G-CSF) and cytokines IL-1β, IL-9, and IL-12p70." (PMID 33919521, 2021). "In CF patients, the expression of IL-9 and IL-9R is increased and is associated with mucus overproduction, but whether and how IL-9 contributes to immunity and pathology in response to the fungal infection in CF is not known." (PMID 28090087, 2017).
gingivitis (4 papers, 2020 to 2024). A disorder involving inflammation of the gums; may affect surrounding and supporting structures of the teeth. "MIP-1β is enriched in healthy gingivae, yet IL-9 is enriched in gingivitis and negatively correlated with MIP-1β: in fact, IL-9 is significantly downregulated at day 3 and day 7 and upregulated at day 28 (versus day 0)." (PMID 33688007, 2021). "SRIB has been previously reported to display anti-inflammatory functions by producing interleukin IL-9, and higher levels of IL-9 and SRIB were detected in gingivitis patients than in healthy individuals." (PMID 35397550, 2022). "It found that interleukin 9 (IL9) had a positive causal relationship with gingivitis, and interleukin 17 (IL17) had a negative causal relationship with gingivitis." (PMID 38812751, 2024).
leukemia (4 papers, 2014 to 2021). A malignant (clonal) hematologic disorder, involving hematopoietic stem cells and characterized by the presence of primitive or atypical myeloid or lymphoid cells in the bone marrow and the blood. "IL-9 overexpression was also observable in leukemic cells from Eμ-TCL1 with overt leukemia, along with a profound decrease in p66Shc expression, and further increased in leukemic cells from Eμ-TCL1/p66Shc−/− mice, demonstrating that p66Shc participates in the control of IL-9 expression." (PMID 34944921, 2021).
malaria (4 papers, 2014 to 2023). Malaria is a serious and sometimes fatal disease caused by a parasite that commonly infects a certain type of mosquito which feeds on humans. "High levels of IL-9 through TGF-β induction were also negatively associated with severe malaria." (PMID 37569646, 2023). "The positive correlation that we observed suggests that the TGF-β–IL-9 connection operates in malaria patients." (PMID 36293524, 2022). "This translated into much weaker correlations of IL-10 with TGF-β1, TGF- β3, and IL-9 than seen between the latter, thus making it a less reliable marker of malaria control." (PMID 36293524, 2022). "Indeed, the treatment of Plasmodium-infected mice with neutralising antibodies to TGF-β exacerbated the malaria disease, while IL-9 played a protective role during experimental chronic infection with T. cruzi by reducing parasite multiplication and invasion." (PMID 36293524, 2022). "Here, we observed that IL-9 plasma concentrations were comparable between controls (1676 ± 560 pg/Ml) and severe malaria patients (1905 ± 534 pg/Ml) but increased more than fourfold (6997 ± 1783 pg/Ml) in mild cases (p < 0.001), showing a striking similarity with TGF-β1 and TGF-β3." (PMID 36293524, 2022). "In addition, and similar to its critical role in the clearance of Trichuris muris, IL-9 could even enhance malaria parasite clearance by its ability to stimulate mast cells, which are essential for resistance to Plasmodium in the mouse." (PMID 36293524, 2022). "This could contribute to the observed upregulation of FOXP3 mRNA in mild malaria since TGF-β and IL-9 both contribute to Treg upregulation." (PMID 36293524, 2022). "Strikingly, those genetic markers are located within chromosome 5q31; noticeably, the distance between D5S642 and the IL9 microsatellite was 3.7 cM, and the one between the IL9 microsatellite and D5S2017 was 6.7 cM, suggesting the existence of several distinct malaria resistance loci in this region." (PMID 24884991, 2014). "IL-9 is a cytokine that is strongly upregulated by TGF-β, and, to the best of our knowledge, IL-9 plasma levels have not yet been studied and compared with TGF-β in malaria patients." (PMID 36293524, 2022). "In our analysis, IL-10 was also increased in patients with mild malaria but, unlike TGF-β and IL-9, its concentration was also significantly higher in severe cases than in controls." (PMID 36293524, 2022).
myocarditis (4 papers, 2016 to 2024). Myocarditis is a condition that is characterized by inflammation of the heart muscle (myocardium). "Collectively, these findings indicate that IL9 overexpression increases the cardio-protective Th2 response in CVB3-myocarditis, decreasing at the same time the detrimental Th17 and Th22 populations at 14 days." (PMID 35508525, 2022). "In this study, the pooled AAV9-mediated overexpression of 60 cytokines in a human Coxsackievirus-B3-induced myocarditis mouse model allowed the identification of five cardioprotective interleukins (IL9, IL3, IL4, IL13, and IL15)." (PMID 35508525, 2022). "A previous experimental study indicated that IL-9 inhibited Coxsackievirus B3 viral replication and diminished the myocarditis induced by infection; these authors suggested that IL-9 reduced the levels of a host cell protein used by the virus to enter the cells." (PMID 34722343, 2021).